BCL10 (BCL10 immune signaling adaptor)
Diseases named in the same sentence as BCL10 in open-access papers (continued):
Sharing a sentence is not in itself a finding about the gene and the disease.
tumor (continued). "Histologically, both masses had tumor cells similar to acinar cells and were positive for BCL-10." (PMID 33319067, 2020). "To further elucidate the role of BCL10 in CD8+ T cells within the CESC immune microenvironment, we successfully established an implanted CESC tumor mouse model." (PMID 40539049, 2025). "During the initial immune surveillance phase, BCL10 controls NF-κB activation through phosphorylation of the CARMA1-IKK, thereby enhancing anti-tumor immunity." (PMID 40539049, 2025). "Multiple mechanisms responsible for the resistance of BTK inhibitors include mutations in BTK and downstream signaling molecules, such as PLCγ2, CARD11, and BCL10 leading to prolonged and BTK-independent NF-κB activation resulting in tumor cell growth." (PMID 37845755, 2023). "In the current study, we demonstrated that inhibition of BCL10 using shBCL10 significantly inhibited the cell proliferation of the three PDAC cell lines and the tumor growth of mice bearing PANC-1 xenograft tumors." (PMID 34412631, 2021). "The nuclear expression levels of BCL10, BCL3, and NF-κB (p65) in tumor cells were also downregulated in shBCL10-transfected PANC-1 group when compared with scrambled PANC-1 group." (PMID 34412631, 2021). "On immunohistochemical staining, the tumor cells of ACC showed diffuse positivity for acinar cell markers, trypsin, and BCL10 and negativity for the ductal marker MUC1." (PMID 32891173, 2020). "In these tumor cells, kinase inactive TAK1 is responsible for BCL10 degradation and NF-κB inactivation." (PMID 30022982, 2018). "In conclusion, long-term stimulation with tumor antigens might lead to increased expression of BCL10, and suppress CD8+ T cells, Th1 cells, and NKT cells while promoting Treg and Th2 cell expansion across multiple tumor types." (PMID 40539049, 2025). "BCL10 acts as a core component of the CBM complex (CARMA1-BCL10-MALT1), mediating NF-κB-dependent immune regulation through dynamic functional switching during tumor immunoediting." (PMID 40539049, 2025). "CARD9 was equally immunoprecipitated from total cell protein lysates of each group, but Bcl10 and MALT1 attached to CARD9 increased nearly 2 and 3 folds respectively on NLGP addition to the tumor-conditioned cells, suggesting the trimolecular complex formation because of the NLGP-transduced signal." (PMID 38649988, 2024). "Tumours were stained negative for desmin, E-cadherin, neurofilament and BCL10." (PMID 41007613, 2025). "Moreover, PCBP1-AS1 also showed a significant negative correlation with FAM3C, BCL10, SLC16A3, WDR1, and other key molecules of tumor malignant behavior." (PMID 38433921, 2024).
cancer (31 papers, 1999 to 2025). A tumor composed of atypical neoplastic, often pleomorphic cells that invade other tissues. "In order to further evaluate the role of this gene in human adult malignancies, we have analysed a series of carcinomas for mutations in the Bcl10 gene." (PMID 10408401, 1999). "It is plausible that the deregulation of genes implicated in DNA damage response and apoptosis, including Bcl10, may contribute to the initiation of cancer." (PMID 37888706, 2023). "Functionally, Tollip and Bcl10 are linked to the regulation of pro-inflammatory responses through the activation of NF-κB, a transcription factor that is pro-tumorigenic and a prime target in human cancer." (PMID 33322811, 2020). "Multi-omics profiling revealed that BCL10 is significantly overexpressed in TIME across most cancers, strongly correlating with immune dysfunction." (PMID 40539049, 2025). "Biopsy and immunohistochemical findings including negative Synaptophysin and Chromogranin A staining and positive Trypsin and BCL10 staining suggested a carcinoma with acinar cell differentiation." (PMID 38625458, 2024). "BCL10, a key participator in the regulation of DNA double-strand breaks repair 33, is commonly involved in promoting the growth and invasion of cancer cells 34-36." (PMID 35371321, 2022). "IPA analysis of these unique up-regulated genes indicated that some genes were associated with cell transformation during cancer progression (ABL1, TRIO, FOSB, NRCAM, TRIB2 and CDK6) and others with cell survival (e.g., BCL10, BBC3, FGF8, HSPA4 and SOD1)." (PMID 29137349, 2017). "The recently described Bcl10 gene has been suggested to be a major target gene for inactivation in a variety of human cancers." (PMID 10408401, 1999). "Interestingly, in the COAD, DLBC, PAAD, READ, and STAD datasets, both IL7 and BCL10 were expressed higher in the cancer group than in the normal group." (PMID 38289597, 2024). "Consistent with this hypothesis, their data indicate that CARMA3 and Bcl10 are required for EGFR-induced NF-κB activation in both EGFR-expressing human cancer cell lines and mouse embryonic fibroblasts." (PMID 30814996, 2019). "However, it is unclear whether prolonged activation of BCL10 within tumors lead to T cell exhaustion and suppress immune responses against cancer." (PMID 40539049, 2025). "CYT-low COAD tumors contained significantly more cancer genes harbored within chromothriptic regions (TCF12, NF1, ERBB2, JUN, JAK1 and BCL10)." (PMID 34316699, 2021). "Aripiprazole was able to modulate the gene expression of certain pro- (Caspases 3, and BCL10, and anti-apoptotic genes (BCL2L1, and c-myc) those play an important role in regulating the apoptosis, and hence progression of cancer." (PMID 32746451, 2020). "The CARD–coiled coil (CC)/Bcl10/MALT1-like paracaspase (CBM) signaling complexes composed of a CARD–CC family member (CARD-9, -10, -11, or -14), Bcl10, and the type 1 paracaspase MALT1 (PCASP1) play a pivotal role in immunity, inflammation, and cancer." (PMID 29881386, 2018). "The transcripts included in the final signature were BCL10, CXCL11, CYBB and GBP1 and, based on their expression levels, our algorithm was able to classify plasma samples into cancer and control with a receiver operating characteristic (ROC) area under the curve (AUC) of 0.92 to 0.95." (PMID 33580122, 2021). "Our results demonstrated that the invasive capabilities of CARMA3- and Bcl10-knockdown H1299 cancer cells were reduced compared to the negative control cells." (PMID 22615840, 2012). "These defects were initially not retained in our filtering, because known cancer genes (NRAS, BCL10, TRIM33, RBM15) are also included in the same deletion and the minimal mutational frequency requirement was not satisfied." (PMID 28147343, 2017).
infection (13 papers, 2010 to 2024). The state of being infected such as from the introduction of a foreign agent such as serum, vaccine, antigenic substance or organism. "In contrast, in SP-A2 mice, the NFκB complex does not appear in the TNF node pathway and the IKK complex appears to be directly activated by BCL10, the expression of which was similar in males and females in SP-A2 and KO male 6 h post-infection." (PMID 32670284, 2020). "The expression of the proapoptotic gene BCL-10 was upregulated in the Axl−/− macrophages after infection." (PMID 32611752, 2020). "Adoptive transfer of Bcl10-/- CD4+ T cells prior to infection partially restored worm growth, resulting in a phenotype that was intermediate between RAG-1-/- recipients of wild type CD4+ T cells and non-reconstituted RAG-1-/- mice." (PMID 20442785, 2010). "Lentiviral infection led to homogenous transduction of Jurkat T-cells as judged by co-expressed surface marker ΔCD2 and equivalent expression of all constructs close to endogenous levels in the BCL10 KO cells." (PMID 30279415, 2018). "Jurkat CARD11 or BCL10 KO T cells were reconstituted by lentiviral transduction and comparable infection rates for epitope-tagged (FS: Flag-StrepTag2) CARD11 and BCL10 constructs were obtained, as determined by co-expression of the surface marker ΔCD2." (PMID 30515170, 2018). "Finally, several pro-apoptotic genes, including Bcl3, Bcl10, Malt1 and Dedd2, were up-regulated in response to muriform cells infection whereas Bcl2l12, coding to anti-apoptotic factor, was down-regulated, suggesting that infection of macrophages with muriform cells could induce apoptosis." (PMID 28355277, 2017). "Likewise, B cell differentiation genes (BCL10, CD72, FOS, PTPRC, SH3BP5, PTPN6, etc.)were also downregulated throughout the infection, correlating with the drop of B cell numbers at D8." (PMID 37146079, 2023). "For their part, pro-inflammatory cytokines triggered by CARD9/Bcl-10/MALT1 below Syk were not impacted by CR3-mediated infection with rBCG::PGL-I." (PMID 31921172, 2019). "PJP is a very common infection in CARD11 deficiency (reported in 75% of identified patients) but is not a reported pathogen in MALT1 and BCL10 deficiency." (PMID 30283440, 2018). "Most interestingly, our data suggest that in VA, the population with the longest co-evolutionary history with MG, the birds decrease the baseline BCL10 gene expression compared to other populations (irrespective of MG infection in model 1, and only in controls in model 2)." (PMID 38370402, 2024). "However, in response to infection, male mice exhibited higher expression levels of CXCL2 (KO, 1A3, and 6A2), SAMHD1 (1A0, 1A3), RSAD2, STAT1, and STAT3 (1A0), MYD88 and PSMB8 (1A3), BCL3, BCL10, CCRL2, IFITM2, RTP4, and ZFP36L1 (6A2), compared to females." (PMID 32670284, 2020).
bacterial infection (3 papers, 2017 to 2024). "The immunomodulatory effects of BCL10 are further documented by the up-regulation of its expression during experimental bacterial infections in cattle and poultry." (PMID 38370402, 2024). "Six immune-related genes were potentially targeted by gga-miR-1416-5p including BCL10, NFKBIA and TLR21, which were important in the response to bacterial infection." (PMID 28086873, 2017). "Knocking down BCL10 led to higher transcriptional levels of STING and TBK1, but not of IRF3 upon the bacterial infection." (PMID 33806598, 2021).
genetic disease (1 paper, 2021). "However, the scarcity of BCL10 deficient patients has prevented gaining detailed knowledge about this genetic disease." (PMID 34868072, 2021).
BCL10 also shares sentences with these, for which no sentence is quoted: combined immunodeficiency (3 papers); fungal infection (3); colon cancer (2); colorectal cancer (2); abdominal aortic aneurysm (1); acute lymphoblastic leukemia (1); airway hyperresponsiveness (1); anaplastic large cell lymphoma (1); atherosclerosis (1); atopic dermatitis (1); autoimmune disease (1); Burkitt lymphoma (1); cervical squamous cell carcinoma (1); chondrosarcoma (1); chronic mucocutaneous candidiasis (1); coagulation disorders (1); COVID-19 (1); gastric lymphoma (1); gastric MALT lymphoma (1); gastroesophageal reflux (1); germ cell tumours (1); glioma (1); head and neck tumours (1); hematologic malignancies (1); inflammatory bowel disease (1); liver cancer (1); lymphoid tumor (1); lymphoplasmacytoid lymphomas (1); malignant mesothelioma (1); multiple myeloma (1).
A further 10 diseases each share a sentence with BCL10 in 1 paper.